UCP1 (uncoupling protein 1)
Diseases named in the same sentence as UCP1 in open-access papers (continued):
Sharing a sentence is not in itself a finding about the gene and the disease.
Obesity (continued). "The possibility to counteract the development of obesity in humans by recruiting brown or brite/beige adipose tissue (and thus UCP1) has attracted much attention." (PMID 37499977, 2023). "Thermogenesis depends on a high mitochondrial density and expression of Uncoupling protein 1 (Ucp1), and serves as protection from hypothermia and, potentially, obesity." (PMID 36895792, 2023). "Mice deficient in the UCP1 are a well-suited animal model to investigate UCP1-independent mechanisms and study human obesity since adults with obesity express only minor amounts of UCP1." (PMID 37240054, 2023). "Conversely, removal of BAT or deletion of uncoupling protein 1 (UCP1) aggravates obesity and/or glucose intolerance in mice." (PMID 37734559, 2023). "As a consequence, stimulated maximal and proton leak respiration, which positively correlates with UCP1 activity, and extracellular acidification were suppressed in active beige adipocytes originated from FTO obesity-risk genotype carriers." (PMID 37416800, 2023). "Although it is easy to state that the mice should be at thermoneutrality for an obesity-augmenting effect of the UCP1 ablation to become manifest, the practical implication of this is not easy." (PMID 37661736, 2023). "Several studies showed an association between UCP1 variants and the susceptibility to MetS, T2DM, and/or obesity in various populations; all these studies were, however, limited to a few selected polymorphisms." (PMID 37107547, 2023). "Supplementation with CTE did not increase the mRNA levels of Pgc-1α but it attenuated the obesity-induced downregulation of Fasn (p < 0.01), Lpl (p < 0.05), Hsl (p < 0.01), Ppar-γ (p < 0.05), Ucp-1 (p < 0.05), β3-Adr (p < 0.05) and Ob-r (p < 0.05)." (PMID 37239868, 2023). "To explore the function of MR in BAT during obesity, we crossed MR-LoxP mice with UCP1-Cre mice to generate BMRKO mice." (PMID 37734559, 2023). "In many studies aimed at increasing thermogenesis with the goal of counteracting the development of obesity, the stated successful endpoint reached has often been increased UCP1 amounts or increased UCP1 gene expression levels." (PMID 37499977, 2023). "The current study opened a new window to adults that obesity induced by UCP1-dependent thermogenic fat inactivation and depletion can be treated by hypothermal experience." (PMID 37240054, 2023). "Thermogenesis induction is essential for the suppression of obesity and mitochondrial biogenesis, through the activation of the thermogenic effector UCP1, and PGC1-α is a crucial thermogenesis driver." (PMID 36839173, 2023). "T. lutea F&M-M36 biomass also contains 0.6% (dry weight) of the carotenoid fucoxanthin; fucoxanthin showed anti-obesity and anti-diabetic effects in mice by promoting the expression of the UCP1 and β3-adrenergic receptors in WAT." (PMID 37233497, 2023). "The obesity-proneness of UCP1 KO mice is normally tested simply by offering the mice what is generally referred to as a high-fat diet." (PMID 37661736, 2023). "This is accomplished by activating the uncoupling protein 1 (UCP1)‐dependent pathway to decrease obesity through thermogenesis and epididymis adipose tissue (EAT) browning." (PMID 38455221, 2023). "Maternal resveratrol supplementation reversed the obesity phenotype in mouse offspring and enhanced UCP1 protein levels in brown and inguinal white adipose tissue but not in epididymal adipose tissue." (PMID 37061742, 2023). "Experimental studies have suggested that omega-6 PUFA leads to white fat deposits and obesity, while omega-3 fatty acids increase thermogenesis through the expression of UCP1 and increase fatty acid oxidation." (PMID 37764855, 2023). "The important role of BAT in obesity resistance of Plin5-Tg mice is further supported by the strongly increased expression of UCP1 and TH upon acute cold exposure, whereas UCP1 expression was unchanged at thermoneutrality." (PMID 37150323, 2023).
Obesity (continued). "Based on the outcomes of the current study, we demonstrated evidence for the potential use of EPA in combating obesity and improving overall metabolic health via alternative UCP1-independent thermogenesis." (PMID 37240054, 2023). "Induction of browning in iWAT by transgenic expression of PR domain-containing 16 (Prdm16) increases Ucp1 mRNA level and protects the mice from diet-induced obesity." (PMID 37465124, 2023). "Modulating several of these pathways in Ucp1-deficient mice, has revealed adaptations in macronutrient utilization and protection from diet-induced obesity, showcasing Ucp1-independent thermogenic pathways." (PMID 37020585, 2023). "A similar type of study also showed that at a thermoneutrality temperature (30 °C), the ablation of UCP-1 in mice resulted in obesity under the influence of a high-fat diet." (PMID 36900198, 2023). "In inbred Lou/C rats, which are a transgenic model of obesity resistance, increased Ucp1 expression was observed in white adipose tissue, potentially contributing to resistance to diet-induced obesity." (PMID 38003681, 2023). "Taken together, AJLE showed anti-obesity properties, including adipogenesis inhibitory effects through the PPARγ-C/EBPs pathway and brown adipocyte induction effect by increasing UCP-1, PRAM16, and BMP7 expression." (PMID 37511251, 2023). "Consistent with Ucp1-independent thermogenic pathways, Ucp1-null mice show varied effects in response to cold exposure and diet-induced obesity, which appear to relate to vivarium temperature conditions and genetics." (PMID 37020585, 2023). "Here we examine if a diet that can activate diet-induced thermogenesis can exploit pre-enhanced amounts of UCP1 to counteract the development of diet-induced obesity." (PMID 37499977, 2023). "To investigate the anti-obesity significance of highly augmented amounts of UCP1 for control of body energy reserves, we physiologically increased total UCP1 amounts by recruitment of brown and brite/beige tissues in mice." (PMID 37499977, 2023). "High-fat diet (HFD) induces obesity and diabetes, and the thermogenic fats burn excess calories to counteract the metabolic consequences of obesity in mice though UCP1 is dispensable." (PMID 39872016, 2023). "For a long time, higher UCP1-dependent thermogenesis was thought to be the reason for obesity resistance and cold endurance of AJ mice, in contrast to strains such as B6." (PMID 36720306, 2023). "We investigated the ability of the exceptionally high amounts of UCP1 that were induced by cold acclimation to protect the mice against the expected obesity when they were exposed to the thermogenesis- and obesity-inducing diet." (PMID 37499977, 2023). "HFD in mice disrupted the normal metabolic cycle, and TRF considered to restore rhythms increased the rhythmic Ucp1 and PPARα expression, which enhanced thermogenesis and resisted obesity." (PMID 37293491, 2023). "CGA reduced body weight and fat deposition by possibly involving in PGC-1α and UCP1 in obesity mouse and HepG2 cells and regulating fatty acid β-oxidation by activating PPARα in the liver." (PMID 37710316, 2023). "The tissue in mice with diet-induced obesity does indeed look atrophied, with large fat droplets, less cytosol per visible area in a microscopy slide, less UCP1 staining per area, less vascularization and innervation per area." (PMID 37661736, 2023). "further found that FAPs provide a likely source for intramuscular adipocytes expressing UCP1 in obesity-resistant Sv129 mice." (PMID 37920255, 2023). "All of this would in itself be a good indication of the significance of UCP1 and brown adipose tissue for human metabolism and obesity propensity." (PMID 37661736, 2023). "Browning of WAT has been proposed as a mechanism to combat obesity and its co-morbidities, and browning is typically defined as an increase in the UCP1 mRNA/protein or an increase in other brown adipocyte genes, such as CPT1b and PDRM16." (PMID 37108770, 2023).
Obesity (continued). "Regarding dietary intervention, limited benefits of EPA in reducing obesity in both WT and UCP1 KO mice occurred at thermoneutrality." (PMID 37240054, 2023). "The tenet described here in general is that obesity normally leads to increases in brown adipose tissue recruitment (UCP1 amount), partially counteracting the obesity." (PMID 37661736, 2023). "Increasing energy expenditure through uncoupling protein 1 (UCP1) activity in thermogenic adipose tissue is widely investigated to correct diet-induced obesity (DIO)." (PMID 37355753, 2023). "The activity of UCP1, a protein in the mitochondrial inner membrane of adipocytes, is the key to the mechanism of treatment for fat browning-induced obesity." (PMID 38139853, 2023). "In conclusion, our data indicated that R. fasciculatum elevated peripheral thermogenic signaling through increased UCP1 via afzelin activation and ameliorated diet-induced obesity." (PMID 35268752, 2022). "The combination of UCP1 and β3AR polymorphisms is related to reduced BAT mass with age, suggesting that aging uncovers the effects of this gene combination on obesity." (PMID 36291357, 2022). "BAT is present throughout the life of mice and provides resistance to diet-induced obesity through UCP1." (PMID 36000239, 2022). "Baicalin, a main component of the root of S. baicalensis, attenuated the HFD-induced obesity through upregulating the expression of thermogenic genes (UCP1 and PGC-1α) in adipocytes." (PMID 35276805, 2022). "According to recent studies, FX processes an anti-obesity activity mostly by stimulating the expression of uncoupling protein-1 (UCP-1) in WAT." (PMID 35983376, 2022). "A recent study in the journal Nature found that IL-27 promotes the browning of adipose tissue by up-regulating the expression of Uncoupling Protein 1 (UCP1) to promote heat production and energy consumption, thereby reducing obesity." (PMID 35938165, 2022). "In these mice, obesity and hypertension appeared earlier and were more severe than in mice with the knockout of UCP1 or TRPV1 alone." (PMID 35043013, 2022). "It was reported that succinate protects against diet-induced obesity by an uncoupling protein (UCP1)-dependent thermogenesis of brown and beige adipose tissue and promotes energy expenditure in mice." (PMID 35685883, 2022). "BAT inhibits obesity by metabolizing lipids via uncoupling protein 1-mediated uncoupled respiration, whereas WAT accumulates lipids." (PMID 35778735, 2022). "Other than UCP1 and the branch metabolism effects induced by Fx, studies also suggest the relationship between obesity and the antioxidative/antiangiogenic effects of Fx." (PMID 35736173, 2022). "Taken together, the possible mechanism of transdermallydelivered SC targeting BAT against obesity development was contributedto the acceleration of UCP1-dependent thermogenesis." (PMID 36281715, 2022). "An extract from Paullinia cupana seeds has been found to reduce obesity by inducing the overexpression of the UCP-1 via activation of AMPK, too." (PMID 36501129, 2022). "Studies have suggested that GM is involved in preventing obesity by enhancing the uncoupling protein 1 (UCP-1)-dependent thermogenesis." (PMID 36161997, 2022). "Previous studies have demonstrated that DIO2, UCP1, and β3AR have a mutual impact on obesity in adulthood." (PMID 36291357, 2022). "A recent report further suggests that gut microbiota mediates the effects of curcumin on enhancing UCP1-dependent thermogenesis and improving high-fat diet-induced obesity in mice." (PMID 36012714, 2022). "In the adipose tissue–UCP1 knockout mice, the ectopic expression of UCP1 in skeletal muscle revealed an essential role of skeletal muscle respiratory uncoupling in preventing diet-induced obesity, insulin resistance, and cholesterolemia." (PMID 35323702, 2022). "UCP-1 activity is a brown fat conversion activity, which is one of the indicators related to fat metabolism and obesity." (PMID 36421434, 2022).
Obesity (continued). "Our data emphasize the importance of maintaining FGF21 sensitivity in adipose tissue during obesity to resist metabolic complications, as seen in UCP1 KO mice, which remain FGF21-sensitive in iWAT despite increased endogenous FGF21 levels." (PMID 36034414, 2022). "In transgenic mice with increased skeletal muscle-specific UCP1 expression, UCP1 activity showed great potential to reduce obesity and inflammation by accelerating skeletal muscle metabolism and energy expenditure." (PMID 36009191, 2022). "We found that the regulatory effect of TRPV1 on LETM1 was critical to restrain obesity and related hypertension, and the knockout of TRPV1 further exacerbated obesity in UCP1 knockout mice, resulting in more severe hypertension." (PMID 35043013, 2022). "This concept appeared to be corroborated by UCP1-KO mice developing obesity at thermoneutrality, an observation as controversial as its apparent implication." (PMID 35269549, 2022). "To determine how TRPV1 deficiency affects obesity induced by UCP1 knockout, we generated TRPV1/UCP1 double knockout mice (TRPV1−/−/UCP1−/−) by crossbreeding TRPV1−/− mice with UCP1−/− mice." (PMID 35043013, 2022). "Here, we show that after long-term high fat diet feeding (HFD), circulating FGF21 levels become similarly high in obese wildtype and obesity-resistant UCP1 KO mice, suggesting improved FGF21 sensitivity in UCP1 KO mice." (PMID 36034414, 2022). "In obese animals, batosomes are enriched with proteins involved in signal transduction, cell communication, the immune response, inflammation, thermogenesis, and as obesity biomarkers including UCP1, Glut1, MIF, annexin A6, CD14, and ceruloplasmin." (PMID 36142750, 2022). "Human brown fat is a potential therapeutic target for preventing obesity and related metabolic diseases by dissipating energy as heat through uncoupling protein 1 (UCP1)." (PMID 35459786, 2022). "In our previous publication, we performed next generation RNA sequencing in several peripheral tissues to gain molecular insights on how FGF21 controls the obesity resistance in UCP1 KO mice." (PMID 36034414, 2022). "Activation of UCP1 by pharmacological drugs has been shown to suppress obesity and improve insulin sensitivity through its thermogenic function." (PMID 35276805, 2022). "UCP1-knock out mice are protected from diet-induced obesity at sub-thermoneutral temperatures, because the alternative thermogenic mechanisms consume more calories to produce the same amount of heat needed for thermoregulation." (PMID 34741717, 2022). "Nevertheless, there is considerable controversy regarding the contribution of brown fat to prevent the development of diet-induced obesity, even though a recruitment of UCP1 in response to HFD feeding has often been reported." (PMID 35269549, 2022). "Experimental data revealed that overexpressing UCP1 in skeletal muscle can accelerate metabolic energy consumption and prevent diet-induced obesity and insulin resistance." (PMID 35323702, 2022). "The anti-obesity effect of FCX in humans and mice is linked to increased uncoupling protein 1 (Ucp1) expression and browning/beiging of WAT." (PMID 35684079, 2022). "Uncoupling protein 1 (UCP1) catalyzes to mitochondrial proton conductance and protection against hypothermia and obesity." (PMID 36207302, 2022). "Chronic AMPK activation, on the other hand, protects against HFD-induced obesity via UCP1 dependent and independent mechanisms." (PMID 35996069, 2022). "Endogenous FGF21 fully mediates obesity resistance in mice with genetic inactivation of the adipose-specific mitochondrial uncoupling protein 1 (UCP1), when fed high fat diets (HFD) at room temperature (representing mild cold conditions)." (PMID 36034414, 2022). "The further identification of substrates involved in Clk action that result in increases of UCP1 and PGC1α will enhance the development of drugs that modulate adipocyte function and revise intervention strategies aimed at obesity management." (PMID 35801494, 2022).
Obesity (continued). "Prdm16 enhances the Ucp-1-mediated thermogenic gene programming in subcutaneous white adipose, promoting energy expenditure and improving metabolism, which resists obesity." (PMID 36422269, 2022). "Regulation of the mRNA expression of UCP-1 in tissues other than BAT by dietary constituents is considered an advanced discovery for effective obesity treatment." (PMID 35983376, 2022). "FX reduces the expression of adipocyte cytokines and exerts anti-obesity effects by increasing the WAT expression of UCP1." (PMID 36432455, 2022). "UCP1 acts in thermogenesis, protects against oxidative stress, and controls energy expenditure, leading to anti-obesity effects." (PMID 35897908, 2022). "Given the adverse effects of obesity on lifespan, these findings point to a role for UCP1 in mitigating the consequences of unhealthy diet on age-related decline of healthspan." (PMID 35406743, 2022). "The decay of SIRT1 as a RIDD target gene is suggested to be the key mechanism involved in the attenuation of obesity conditions, along with a well-established SIRT1-PGC-1α-linked UCP1-associated energy controlling mechanism." (PMID 35458241, 2022). "Like traditional UCP1-dependent thermogenesis, the UCP1-independent thermogenic machinery is also sufficient to regulate whole-body energy homeostasis and protect against diet-induced obesity and related metabolic dysfunction." (PMID 35493493, 2022). "The activation of UCP-1 provides benefits against obesity, decreases fat mass, and improve insulin sensitivity." (PMID 34721992, 2021). "Adding to the complex relationship between obesity and increased FGF21, it has been recently shown that UCP1-KO mice, which are resistant to diet-induced obesity at ambient 230C, displayed a 2.5-fold increase in serum FGF21 levels when fed a HFD." (PMID 35046901, 2021). "The present study indicates that BAT and WATs (iWAT and eWAT) play distinct roles in maintaining systemic energy homeostasis in response to either ANP treatment or HFD-induced obesity, as shown by the UCP1 expression in each adipose tissue." (PMID 34465848, 2021). "Studies conducted in a UCP1/FGF21 double knockout (dKO) model have demonstrated a full reversal of obesity resistance in dKO mice by inhibiting the metabolic reprogramming of WAT genes responsible for enhanced lipid and oxidative metabolism." (PMID 34185433, 2021). "Fas mutant mice show a lean phenotype and prevent HFD-induced obesity by upregulating the expression levels of UCP1, IL-4, and IL-10 in WAT." (PMID 34576181, 2021). "It has been established that adiposity is inversely correlated to BAT mass or activity in adult human, which protects against obesity and related metabolic disorders by promoting energy expenditure via the activity of uncoupling protein 1 (UCP1)." (PMID 34017266, 2021). "Downregulation of UCP-1 impairs energy consumption and heat production, which accelerates the progression of lipid accumulation and obesity." (PMID 34677392, 2021). "The core ATP produce and thermo‐control gene Ucp1 as well as mitochondrial function gene Cox8b is related to the obesity and diabetes." (PMID 33369170, 2021). "Loss of Ucp1 also causes whitening of BAT, decreasing its protective role against the development of insulin resistance, type 2 diabetes, and obesity." (PMID 34829617, 2021). "To elucidate the mechanism underlying PVAT browning–evoked protection against CVDs, we investigated the role of UCP1 on obesity/diabetes-induced endothelial dysfunction, vascular inflammation, and atherosclerosis in both mice and pigs." (PMID 34878840, 2021). "Transgenic mice with upregulation of UCP1 in WAT showed resistance to diet-induced obesity even when fed a high-fat diet." (PMID 34829617, 2021). "Although the mechanism underlying obesity‐resistant phenotype of HFD‐fed Rptorob−/− mice requires further investigation, the mechanism is likely to involve the upregulation of Ucp1 expression in the WAT depots of Rptorob−/− mice." (PMID 33977204, 2021).